SH3GL3 (SH3 domain containing GRB2 like 3, endophilin A3)
Description:
Implicated in endocytosis. May recruit other proteins to membranes with high curvature (By similarity).
Synonyms: CNSA3; SH3D2C; SH3P13; EEN-B2; HsT19371
Tractability: Antibody: UniProt places it where antibodies can reach, with medium confidence. PROTAC: its protein half-life has been measured.
Gene: Protein-coding gene on chromosome 15 (83,447,228 to 83,618,743, forward strand). Ensembl gene ENSG00000140600.
Subcellular location: Cytoplasm; Early endosome membrane
Subcellular location (Human Protein Atlas): Mitochondria
Pathways (Reactome):
Signal Transduction: EGFR downregulation; NGF-stimulated transcription; Negative regulation of MET activity
Vesicle-mediated transport: Cargo recognition for clathrin-mediated endocytosis; Clathrin-mediated endocytosis
Disease: InlB-mediated entry of Listeria monocytogenes into host cell
Gene Ontology:
Molecular function: identical protein binding; protein binding; protein-macromolecule adaptor activity
Biological process: central nervous system development; endocytosis; membrane organization; signal transduction; negative regulation of clathrin-dependent endocytosis; positive regulation of neuron differentiation; regulation of clathrin-dependent endocytosis
Cellular component: cytoplasm; cytosol; early endosome membrane; glutamatergic synapse; membrane; presynapse; acrosomal vesicle; early endosome; postsynaptic density, intracellular component; postsynaptic endosome
Genetic constraint (gnomAD): Loss-of-function variants: 5 observed, 7.24 expected, observed/expected ratio (o/e) 0.69, 90% interval 0.36 to 1.43. That is too few expected variants to judge how well the gene tolerates losing a copy. Missense variants: 70 observed, 80.28 expected, observed/expected ratio (o/e) 0.87, 90% interval 0.72 to 1.06. Synonymous variants: 32 observed, 29.94 expected, observed/expected ratio (o/e) 1.07, 90% interval 0.81 to 1.43.
Homologues: Orthologues: macaque SH3GL3 (98% identical), chimpanzee SH3GL3 (96% identical), guinea pig SH3GL3 (95% identical), pig SH3GL3 (95% identical), mouse Sh3gl3 (86% identical), rat Sh3gl3 (86% identical), rabbit SH3GL3 (78% identical), tropical clawed frog sh3gl3 (75% identical), zebrafish sh3gl3a (71% identical), Drosophila melanogaster EndoA (52% identical), Caenorhabditis elegans unc-57 (49% identical). Paralogues in human: SH3GL1 (70% identical), SH3GL2 (69% identical), SH3GLB2 (27% identical), SH3GLB1 (27% identical), SORBS1 (21% identical), SH3D19 (20% identical), SORBS2 (20% identical), SH3RF3 (18% identical), SH3RF1 (17% identical), NCF4 (15% identical), SORBS3 (15% identical), SH3RF2 (12% identical).
Diseases named in the same sentence as SH3GL3 in open-access papers:
SH3GL3 is named in the same sentence as 18 diseases in open-access papers, as found by Europe PMC text mining. Sharing a sentence is not in itself a finding about the gene and the disease. The quoted sentences say what the papers report.
lung carcinoma (4 papers, 2017 to 2025). "SH3GL3 has been implicated as a tumor suppressor in glioblastoma and lung cancer, as well as in cell migration and invasion in myeloma, and has been previously identified in colorectal cancer GWAS associated with colorectal cancer." (PMID 37345113, 2023). "Compared to healthy counterparts, SH3GL3 expression is also reduced in lung cancer tissues, where upregulation of the long noncoding mRNA MIR210HG leads to the recruitment of the DNA methyltransferase DNMT1 to the SH3GL3 promoter, inhibiting its transcription." (PMID 40986063, 2025). "Lung cancer-specific cDMCs were found at the promoters of SH3GL3, IGF2, and TMEFF2." (PMID 28751909, 2017).
myeloma (4 papers, 2016 to 2025). "In CD138-negative multiple myeloma clonogenic cells, high SH3GL3 expression activates PI3K and FAK kinases to enhance migration and invasion, promote stemness, and increase the expression of multidrug resistance markers leading to chemoresistance." (PMID 40986063, 2025). "Conversely, SH3GL3 overexpression is detected in multiple myeloma, colon cancer, and melanoma specimens, where it promotes tumorigenesis." (PMID 40986063, 2025). "Inhibition of PI3K using LY294002 also abrogated SH3GL3-induced migration and invasion in myeloma cells." (PMID 27683032, 2016). "Elevated expression of stem cell and multi-drug resistant markers were seen in the myeloma cells with overexpressed SH3GL3; while knocking-down SH3GL3 reduced the expression of these markers." (PMID 27683032, 2016). "Our findings indicate that SH3GL3 plays an important role in myeloma cell migration/invasion, stemness and chemo-resistance." (PMID 27683032, 2016). "Our study indicates that SH3GL3-activated myeloma cell migration/invasion is regulated through the activation of FAK signaling pathways." (PMID 27683032, 2016). "To further confirm the role of SH3GL3 in regulating myeloma cell migration and invasion, we knocked down the expression of SH3GL3 using SH3GL3 shRNA in U266 cells." (PMID 27683032, 2016). "We, therefore, assessed the status of FAK activation in myeloma cells with overexpressed or silenced SH3GL3." (PMID 27683032, 2016). "To test if SH3GL3 plays a role in myeloma cell migration and invasion, we first overexpressed SH3GL3 in a myeloma cell line." (PMID 27683032, 2016). "A similar pattern of changes in the phosphorylated protein levels of p85-PI3K was observed in the myeloma cells with reduced- or over- expression of SH3GL3." (PMID 27683032, 2016). "Overexpression of SH3GL3 in the myeloma cells induced the specific characteristics of stem cells, including the enhanced expression of prototypical stem cell genes and drug resistant genes." (PMID 27683032, 2016). "Taken together, these results suggest that SH3GL3 plays a potential role in the stemness and drug resistance of myeloma cells to BTZ and melphalan." (PMID 27683032, 2016). "We then sought to determine the signaling pathways involving in the SH3GL3-activated migration of myeloma cells." (PMID 27683032, 2016). "Knocking-down SH3GL3 using shRNA reduced myeloma cell migration and invasion and decreased the stemness and chemo-resistance." (PMID 27683032, 2016). "In contrast, overexpression of SH3GL3 increased myeloma cell migration/invasion and enhanced the stemness and chemo-resistance of myeloma stem cells." (PMID 27683032, 2016). "Thus, knocking-down SH3GL3 appears to play a critcal role in decreasing myeloma cell migration and invasion." (PMID 27683032, 2016). "Our data suggest that SH3GL3 plays an important role in migration and invasion of myeloma cells." (PMID 27683032, 2016). "Activation of FAK and PI3K were required for SH3GL3-increased myeloma cell migration/invasion." (PMID 27683032, 2016). "Our data indicated that overexpression of SH3GL3 enhanced migration and invasion of myeloma cells." (PMID 27683032, 2016). "The SH3GL3-mediated myeloma cell migration/invasion is mediated by FAK/PI3K signaling pathway." (PMID 27683032, 2016). "Conversely, overexpression of SH3GL3 increased myeloma cells migration/invasion." (PMID 27683032, 2016). "Human H929 myeloma cells expressed a relative low level of SH3GL3." (PMID 27683032, 2016). "Herein, we found SH3GL3 was highly expressed in the CD138-negative (CD138−) myeloma cells." (PMID 27683032, 2016). "Silencing SH3GL3 using shRNA reduced myeloma cells migration/invasion." (PMID 27683032, 2016). "In this study, we have demonstrated that SH3GL3 enhanced the stemness of myeloma cells." (PMID 27683032, 2016). "Moreover, SH3GL3 is also associated with the stemness and chemo-resistance of CD138− myeloma cells." (PMID 27683032, 2016).
myeloma (continued). "We have demonstrated the distinct expression of SH3GL3 in CD138− and CD138+ U266 myeloma cells consistent with the data from microarray analysis." (PMID 27683032, 2016).
colon cancer (3 papers, 2022 to 2025). "Promoter DNA methylation of the SH3GL3 gene was previously inversely correlated with its expression in human colon cancer cell lines versus matched double knockout cell lines for DNMT1 and DNMT3b77." (PMID 36585414, 2022). "In colon cancer, SH3GL3 expression increases in higher-grade tumors, and EndoA3 supports two pro-tumoral mechanisms: (i) cytosolic EndoA3 binds to the GEF Tiam1, activating Rac1 and subsequent cell migration, and (ii) membrane-associated EndoA3 promotes proliferation via its endocytic activity." (PMID 40986063, 2025).
colorectal cancer (3 papers, 2020 to 2023). A primary or metastatic malignant neoplasm that affects the colon or rectum. "SH3GL3 and BNC1 are both neither reported in the context of UF, however, SH3GL3 is reported as a colorectal cancer-associated gene, and BNC1 is reported to have association with pancreatic cancer." (PMID 31488892, 2020).
glioma (2 papers, 2016 to 2025). A benign or malignant brain and spinal cord tumor that arises from glial cells (astrocytes, oligodendrocytes, ependymal cells). "Like SH3GL1, SH3GL3 expression is lower in glioblastoma compared to healthy brain tissues, with further reduction in higher-grade gliomas, suggesting tumor- suppressive roles." (PMID 40986063, 2025). "However, SH3GL3 expression is reported to be upregulated in glioma infiltration zones, as well as in non-functioning pituitary adenomas." (PMID 40986063, 2025).
pancreatic cancer (2 papers, 2020). "For instance, GPR87 plays a critical oncogenic role in pancreatic cancer progression, and SH3GL3 is a novel invasion-associated candidate gene that likely contributes to the invasive genotype of malignant gliomas." (PMID 32411243, 2020).
Huntington disease (1 paper, 2026). Huntington disease (HD) is a rare neurodegenerative disorder of the central nervous system characterized by unwanted choreatic movements, behavioral and psychiatric disturbances and dementia. "We demonstrate the new experiment by characterizing, for the first time, pico- to nanosecond dynamics along a 16-residue polyglutamine stretch within the protein huntingtin, the causal agent of Huntington's disease, as well as millisecond conformational exchange in the SH3GL3 protein." (PMID 41703747, 2026).
liver cancer (1 paper, 2017). An epithelial or non-epithelial malignant neoplasm that arises from the liver. "In the comparison between the liver cancer and the other cancer groups, cDMCs (FDR < 0.0001) were detected at the promoters of the SPARC, NEUROG1, SH3GL3, and ITGA4 genes." (PMID 28751909, 2017).
medulloblastoma (1 paper, 2022). A malignant, invasive embryonal neoplasm arising from the cerebellum. "Worth noting is that the ADAMTSL3--SH3GL3 circular fusion is also found in medulloblastoma, along with two other ADAMTSL3--SH3GL3 circular fusions encompassing the same SH3GL3 exon and one SH3GL3--ADAMTSL3 circular fusion encompassing the same ADAMTSL3 exon." (PMID 35804907, 2022).
melanoma (1 paper, 2020). A malignant, usually aggressive tumor composed of atypical, neoplastic melanocytes. "Our signature consists of diverse genes comprising protective (ATP1B1, CDAN1, FAU, and TNFSF14)) and risky (GPR87, KIT, SH3GL3, and PVRL1), which could be considered gene-related protective and risk patterns in melanoma." (PMID 32411243, 2020). "In our study, we identified two gene expression patterns and generated an 8-gene-based (GPR87, KIT, SH3GL3, PVRL1, ATP1B1, CDAN1, FAU, and TNFSF14) gene signature that could recognize melanoma patients with a high risk of unfavorable clinical outcomes." (PMID 32411243, 2020). "Finally, eight genes (GPR87, KIT, SH3GL3, PVRL1, ATP1B1, CDAN1, FAU, and TNFSF14) were identified to be closely associated with the OS in melanoma." (PMID 32411243, 2020). "All eligible gene sets were analyzed, and the 8 genes (GPR87, KIT, SH3GL3, PVRL1, ATP1B1, CDAN1, FAU, and TNFSF14) with the greatest prognostic impact on melanoma." (PMID 32411243, 2020). "We identified an 8-gene signature (i.e., GPR87, KIT, SH3GL3, PVRL1, ATP1B1, CDAN1, FAU, and TNFSF14) with independent prognostic value on melanoma." (PMID 32411243, 2020).
SARS-CoV infection (1 paper, 2014). "We found that genes such as IL6, Sh3gl3, and Atxn10, which had previously been associated with different phenotypic outcomes in response to IAV infection, also expressed different isoforms in response to SARS-CoV infection." (PMID 24902603, 2014).
tumor (5 papers, 2022 to 2025). "SH3GL3 was also suggested to be a tumor suppressor of LC as its overexpression significantly suppresses cell proliferation and migration of LC cells." (PMID 36067196, 2022). "Similarly, lower SH3GL3 expression in metastatic versus non-metastatic oral squamous cell carcinoma supports tumor suppressive roles." (PMID 40986063, 2025).
infection (2 papers, 2012 to 2016). The state of being infected such as from the introduction of a foreign agent such as serum, vaccine, antigenic substance or organism. "Infection of cells with SH3GL3 shRNA resulted in a ~80% reduction in SH3GL3 expression, determined using qRT-PCR (bottom)." (PMID 27683032, 2016). "For example, Sh3gl3 (or endophilin A3) has been observed binding with a number of proteins, including Mta1, and may be involved in endocytosis, although the role this might play in infection is not clear." (PMID 22384400, 2012).
SH3GL3 also shares sentences with these, for which no sentence is quoted: cancer (3 papers); glioblastoma (1); malignant glioma (1); multiple myeloma (1); pilocytic astrocytoma (1).